LGALS9 (galectin 9)
Diseases named in the same sentence as LGALS9 in open-access papers (continued):
Sharing a sentence is not in itself a finding about the gene and the disease.
tumor (continued). "However, in T-cell/tumour-cell co-culture environments, galectin-9 induces T-cell apoptosis, which can be blocked by galectin-9 antibodies." (PMID 37371482, 2023). "Furthermore, we added a neutralizing antibody against galectin-9 into a tumor-infiltrating mast cell/CD8+ T-cell co-culture system." (PMID 37042867, 2023). "In HCCs, galectin-9 can potentially regulate tumor progression directly and indirectly." (PMID 37047155, 2023). "HAVCR2/galectin-9 interaction attenuated T-cell expansion and effector function in the tumor microenvironment and chronic infections;Contributes to the formation of tumors through the transformation of cancer cells, regulation of the cell cycle, angiogenesis and cell adhesion." (PMID 36675020, 2023). "In addition to PDL1, EBVaGCs express higher levels of CD155/PVR, CEACAM1, and galectin-9 mRNAs, which represent known anti-tumor immunity genes that antagonize T cell responses." (PMID 36680216, 2023). "In addition, TIM-3/Galectin 9 (Gal-9) expressed on the surface of leukemic stem cells (LSCs) elevates the number of infiltrating MDSCs and TAMs, leading to impaired anti-tumor immune responses." (PMID 36810098, 2023). "Nevertheless, galectin-9 blockade by antibodies also acts directly on tumor cells." (PMID 36703969, 2022). "Our study implied that the combination of PD-1 and LGALS9 inhibition and induction of target cell pyroptosis could possibly inhibit tumor proliferation and improve patient survival of MIBC." (PMID 35479097, 2022). "For example, we described important roles of galectin-1 and galectin-9 in tumor angiogenesis." (PMID 36497271, 2022). "The upregulation of Ctla4 and Lag3 was rather specific as no significant changes were observed in mRNA levels of Cd80 and Cd86 (two CTLA4 ligands present in the antigen-presenting (tumour) cells), Tim-3/Galectin-9 (Havcr2/Lgals9), and Pd-l1 (Cd274) immune checkpoints." (PMID 36433941, 2022). "We adopted the algorithm and found that macrophages with high expression levels of LGALS9 could interact with exhausted CD8 T cells expressing high levels of HAVCR2 in tumor tissues in CCAs." (PMID 36531216, 2022). "The expression and prognostic value of galectin-9 seems to be tumor type dependent." (PMID 36527024, 2022). "The authors describe molecules specific to TEVs, such as S100A4, S100A13, BSG, LGALS9, which may induce immune suppression and tumor-promoting inflammation." (PMID 36498469, 2022). "It was demonstrated that tumor-infiltrating γδ T cells with higher expression of programmed cell death ligand 1 (PD-L1) and Galectin-9 (Gal-9) could inhibit the effector activity of conventional αβ T cells." (PMID 36499125, 2022). "Galectin-9 functions as a modulator of the anti-tumor immune response." (PMID 36612107, 2022). "Galectin-9 is overexpressed on tumor cells in lesional skin of CTCL." (PMID 35677161, 2022). "Although galectin-9 (Gal-9) is highly expressed on lesional skin, in the serum and secreted in higher amounts by patients’ tumor cells, high doses of exogenous Galectin-9 induce apoptosis on CTCL cell lines in vitro and reduce T-cell tumor formation on a murine model." (PMID 35055124, 2022). "As the galectin-9 function remains poorly understood, further research is needed to clarify whether it has a possible tumorigenic role or tumor-suppressing activity." (PMID 36209270, 2022). "Several clinical trials are also working on combined blockade of TIM3/galectin-9 and PD-1/PD-L1 pathways (NCT02817633, NCT03099109, NCT02608268), and other clinical trials focusing on the combination of anti-TIM3/galectin-9 and anti-PD-1/PD-L1 in tumor immunotherapy will be the new strategy." (PMID 36428567, 2022). "In addition, exosome LGALS9 can regulate systemic anti-tumor immunity by inhibiting cytotoxic T-cell activation in cerebrospinal fluid and antigen presentation by dendritic cells." (PMID 36213111, 2022). "Certain galectin-9 signaling pathways also varied between tumor regions." (PMID 35584630, 2022).
tumor (continued). "Furthermore, galectin-9 on both γδ T cells and pancreatic tumor cells has been shown to bind dectin-1 on tumor-infiltrating macrophages, leading to M2 macrophage polarization and subsequent downregulation of IFN-γ and TNF-α production by γδ T cells." (PMID 35880177, 2022). "However, in cancer, galectin-9 both promotes tumor development and inhibits tumorigenesis and transformation, depending mainly on the binding of galectin-9 to T cells and other tumor cell surface receptors." (PMID 36428567, 2022). "The intensity of galectin-9 in the tumor was positively correlated with CD8 + cells and CD3 + cells, indicating that high galectin-9 expression may control the number of T cells in the TME." (PMID 36527024, 2022). "However, tumor tissue exhibited higher levels of immune checkpoint-related ligand-receptors, such as LGALS9-HAVCR2, LAGALS9-CD44, ICOSL-ICOS, ICOSL-CTLA4, and ICOSL-CD28." (PMID 35812401, 2022). "The interaction between TIM3 and Galectin-9 creates an inhibitory tumor microenvironment." (PMID 36358792, 2022). "Therefore, we proposed that global down-regulation of MHC-I molecules and upregulation of galectin 9 collaboratively contributed to tumor evasion from cytolytic CD8+ TIL-mediated antitumor immunity in the TCM group." (PMID 35241665, 2022). "Notably, in the tumor tissues, we found that only the cells in VEGFA_MACRO interacted with those in TIGIT_CD8 via LGALS9/HAVCR2." (PMID 36531216, 2022). "Through interaction with receptors on the surface of T cells, galectin-9 could induce their apoptosis and enhance the tolerance toward tumor cells." (PMID 36612107, 2022). "Therefore, combined blockade of TIM-3/galectin-9 and PD-1/PD-L1 pathways is of great importance in anti-tumor immunotherapy." (PMID 36428567, 2022). "In addition, Galectin-9 induces CW-2 cells to move into G0/G1 cycle arrest, and exerts in tumor growth inhibition." (PMID 36358792, 2022). "Similarly, stromal B7H3 and Galectin-9 coexpression was correlated with tumor necrosis and surrounding muscle invasion of tumors." (PMID 35145510, 2021). "However, B7H3, IDO-1 and Galectin-9 positivity on tumor cells were only seen in 21.0% of cases, despite all showing predominantly stromal expression." (PMID 35145510, 2021). "Furthermore, tumor galectin-9 interacts with dectin-1 on macrophages to promote their tolerogenic program." (PMID 34572756, 2021). "Tumor cells can exhibit a prominent expression of the PD-1 ligands PD-L1 and PD-L2, and also produce the Tim-3 ligand Galectin-9, and may thus directly contribute to maintain the exhausted state of infiltrating T cells." (PMID 33885944, 2021). "However, the concentrations of lectin required to induce cell death (in the order of nM) are unlikely to be reached in the tumor-draining lymph nodes, precluding any pro-apoptotic role of tumor-derived galectin-9 at this anatomical localization." (PMID 34572756, 2021). "As a consequence of their high levels of Tim-3, Tregs are very sensitive to the galectin-9 levels in the tumor microenvironment, and this galectin-9/Tim-3 signaling pathway plays a major role in dampening any potentially lymph node-elicited, anti-tumor immune response." (PMID 34572756, 2021). "One major mechanism identified was the upregulation of PD-L1 and galectin-9 in the tumor." (PMID 33408092, 2021). "Furthermore, it was also nicely demonstrated that tumor-derived galectin-1 upregulates PD-L1 and galectin-9 in endothelial cells." (PMID 34572756, 2021). "Lactate secretion can also be induced by PKM2 up-regulation, resulting in increased expression of Galectin-9 through NF-κB signaling to promote tumor progression—knocking down Galectin-9 could notably enhance the killing effect of NK cells." (PMID 34638609, 2021). "Indeed PD-L1 and galectin-9 were previously reported to be expressed not only by tumor cells and macrophages, but also by Treg, NK cells, fibroblasts, and endothelial cells." (PMID 34921143, 2021).
tumor (continued). "Indeed, tumor-derived galectin-1 remodels the local endothelium in a way that galectin-9 and PD-L1 are upregulated to prevent the lymphocyte infiltration of tumors." (PMID 34572756, 2021). "TIM-3/Galectin-9 suppresses tumor immunity by negatively regulating T cells." (PMID 34743730, 2021). "Furthermore, galectin-9 contained in tumor-derived exosomes attracts regulatory T cells towards tumors." (PMID 34572756, 2021). "Galectin-9 (Gal-9) is a multifunctional member of the galectin family expressed in various cell types and involved in cell proliferation, differentiation, inflammation, tumor and immune cell formation." (PMID 33692448, 2021). "Finally, the authors reported a correlation between galectin-9 expression in tumor cells and TIM-3 expression on TILs." (PMID 35008740, 2021). "TIM-3 and galectin-9 protein expression were also correlated in tumor samples." (PMID 33664848, 2021). "However, as tumor settles as a chronic disease, galectin-9 expression correlates with a poor prognostic value and often associates with immune evasion." (PMID 34572756, 2021). "For instance, the interaction between PD-L1 expressed by tumor cells and PD-1 on DCs or the binding of galectin-9 present on tumor cells with TIM-3 expressed on some DC populations, which are known to influence DC functions, could be involved." (PMID 34847189, 2021). "It has been proven that Galectin-9 expression is closely correlated with the growth and metastasis of many solid cancers by inducing apoptosis of specific T cell subpopulations to mediate tumor immune escape." (PMID 35145510, 2021). "Galectin-9, a tandem-repeat galectin, can either promote or suppress tumor growth and metastasis, depending on whether it acts on immune or tumor cells." (PMID 35008740, 2021). "Therefore, tumor galectin-9 plays a significant role in controlling myeloid cell’s properties, T cell activation and also in controlling the effector phase of anti-tumor immune responses." (PMID 34572756, 2021). "Therefore, tumor secreted galectin-9 can shape the available T cell repertoire by a direct action on resting T cells without any antigen stimulation." (PMID 34572756, 2021). "Tumor-infiltrating T cells showed higher expression of galectin 9 than normal T cells." (PMID 34439378, 2021). "Moreover, it has been confirmed that TIM-3/Galectin-9 signaling is a key pathway for tumor immune escape." (PMID 34743730, 2021). "Galectin-8 and galectin-9 both have two carbohydrate recognition domains and are tandem repeat galactosins that regulate a variety of biological functions, including cell aggregation, cell adhesion, and tumor cell apoptosis." (PMID 34093804, 2021). "However, 24, 6, 12, 21 and 6 patients displayed higher HHLA2, B7H3, IDO-1, PD-L1 and galectin-9 expression in the tumor subregion, respectively." (PMID 35145510, 2021). "Given the presence of galectin-9 on tumor and immune cells, we hypothesized that a relevant amount of soluble galectin-9 should also be present in PDAC patients." (PMID 32055023, 2020). "The expression of LGALS9 was almost undetectable in the CSF of GL-261 LGALS9−/− tumor-bearing mice." (PMID 33093453, 2020). "Interestingly, the initial exposure to GL-261 LGALS9−/− cells led to resistance to challenge with GL-261 WT cells, resulting in tumor growth inhibition and improved survival rates." (PMID 33093453, 2020). "The expressions of Galectin-3 and Galectin-9 in tumor tissue and adjacent non-tumor tissue." (PMID 32995093, 2020). "Tumor-infiltrating T cells contained more galectin-9 compared with T cells from matched blood." (PMID 32055023, 2020). "Galectin-9 was commonly found in the stroma immediately adjacent to tumor cells." (PMID 32486344, 2020). "Increasing evidence show that tumor derived exosomes induce tumor immune escape by impairing the function of immune cells, incuding T cells, NK, DC, through the enrichment of some biological proteins such as PD-L1 or galectin-9 on exosome in different cancer." (PMID 32901082, 2020).
tumor (continued). "Furthermore, galectin-9 blockade expanded and activated tumor-infiltrating CD4+ and CD8+ T cells, but only in γδ T cell-competent hosts." (PMID 32055023, 2020). "Notably, tumor samples expressed galectin-9 either simultaneous high on T-cell subsets or myeloid cells." (PMID 32055023, 2020). "Furthermore, blood immune cells in PDAC patients had higher galectin-9 expression compared with healthy controls, suggesting the existence of a local and systemic tumor-dependent factor driving galectin-9 expression in human PDAC." (PMID 32055023, 2020). "In conclusion, we reveal that GBM cell-derived exosomal LGALS9 acts as a major regulator of tumor progression by inhibiting DC antigen presentation and cytotoxic T-cell activation in the CSF and that loss of this inhibitory effect can lead to durable systemic antitumor immunity." (PMID 33093453, 2020). "We concluded that GBM cell-derived exosomal LGALS9 acts as a major regulator of tumor progression by inhibiting DC antigen presentation and cytotoxic T-cell activation in the CSF and that loss of this inhibitory effect can lead to durable systemic antitumor immunity." (PMID 33093453, 2020). "Since virus-associated type I IFN upregulates inhibitory receptors on CAR T cells as well as PD-L1 and Galectin 9 on tumor cells, we reevaluated the therapeutic potential of CAR T cells with VSVGFP in combination with a cocktail of anti-PD1, anti-TIM3, and anti-LAG3." (PMID 32581235, 2020). "Similarly, paired analysis of immune checkpoint ligands clearly demonstrated that ICOSL, 4-1BBL, OX40L, and Galectin 9 were significantly elevated in tumor tissues compared with non-tumor tissues." (PMID 33552954, 2020). "Tumor and immune cells both had significant galectin-9 expression." (PMID 32055023, 2020). "Our work suggests that epigenetic mechanisms may regulate the expression of the LGALS9 gene during tumor transformation." (PMID 32902187, 2020). "Galectin-9 (Gal-9), expressed in various tumors has a key role in tumor immunity." (PMID 32039024, 2019). "Inhibition of galectin-9 leads to significant tumour regression in a mouse model." (PMID 31832021, 2019). "Overall, it appears that galectin-9 could protect the tumor which produces it in order to evade host immune attack, but this may not promote metastasis." (PMID 31354733, 2019). "Additionally, LGALS9 is expressed by tumor cells which can have diverse effects on different immune cells in the tumor microenvironment." (PMID 31747929, 2019). "Galectin-9 (Gal-9) enhances tumor immunity mediated by T cells, macrophages, and dendritic cells." (PMID 31146370, 2019). "However, galectin-9 overexpression exerts anti-tumor effects both in vitro and in vivo, effects that contrast with those of EZH2 but parallel with those of miR-22." (PMID 29316949, 2018). "Interestingly, IFN-γ produced by tumor-infiltrating lymphocytes induces galectin-9 production by Küpffer cells." (PMID 29389859, 2018). "In summary, the high expression level of galectin-9 in primary cancer lesions promoted cell-matrix interactions, and metastatic lesions displayed decreased galectin-9 expression, suggesting that galectin-9 might suppress tumor metastasis." (PMID 29389859, 2018). "Moreover, we showed that galectin-9 overexpression functions as a tumor suppressor and thus inhibits tumorigenesis both in vitro and in vivo." (PMID 29316949, 2018). "It has been reported that IFN-γ can stimulate galectin-9 expression in endothelial cells, and our previous study showed that IFN-γ secreted by tumor infiltrating T cells induced galectin-9 expression in Kupffer cells, especially in hepatitis virus-associated HCC." (PMID 29316949, 2018). "Some have supposed that galectin-9 has dual-functionality, and it has been proposed that galectin-9 expression may be lost during tumor progression after the initial up-regulation of the protein establishes a tumorigenic environment." (PMID 29316949, 2018).
tumor (continued). "Finally, the patients with recurrent NPC had a high percentage of Galectin-9+ tumour cells accompanied by a low percentage of CD8+ lymphocytes and high percentages of Foxp3+ and Tim-3+ lymphocytes." (PMID 28871094, 2017). "Because patients with recurrent NPC in our series had a significantly higher percentage of Galectin-9+ tumour cells, we speculate that the initial treatment may have an important effect on tumour selection." (PMID 28871094, 2017). "Subsequently, these Galectin-9+ tumour cells had selective growth advantage in recurrent NPC." (PMID 28871094, 2017). "Although a high percentage of Galectin-9+ tumour cells and a high percentage of Foxp3+ lymphocytes in the tumour microenvironment were only marginally significant, a low percentage of CD8+ lymphocytes was a significant risk factor for relapse-free survival and overall survival." (PMID 28871094, 2017). "Therefore, we evaluated the paired immunologic expression of CD8+ lymphocytes, CD4+ lymphocytes, Foxp3+ lymphocytes, and the Galectin-9/Tim-3 pathway in the tumour microenvironment between primary and recurrent NPC from 95 patients." (PMID 28871094, 2017). "Furthermore, the increased percentages of Galectin-9+ tumour cells and Foxp3+ lymphocytes and the decreased percentage of CD8+ lymphocytes significantly differed between primary and recurrent NPC." (PMID 28871094, 2017). "We first explored whether the secretion of galectin-9 from tumor cells had a chemotactic effect on migration in NK cells." (PMID 27028892, 2016). "Furthermore, it has been reported that galectin-9 exerted immunoregulatory roles in tumor microenvironment." (PMID 27028892, 2016). "In the cases studied in this report, we observed upregulation of not only TIM-3 on T cells but Galectin-9 on tumour cells in the case of Kras mutant tumours, indicating that resistance to PD-1 therapy can be driven by coordinated interactions among the tumour and neighbouring immune cells." (PMID 26883990, 2016). "We confirmed a significant elevation in the expression of lectin, galactoside-binding, soluble, 9 (Lgals9), which encodes Galectin 9, in sorted CD45−EpCAM+ tumour samples from the anti-PD-1-resistant Kras tumours as compared with untreated Kras tumours at both RNA and protein level." (PMID 26883990, 2016). "However, in the corresponding tumor tissue samples, only 58% (22 out of 38 cases) were positive for galectin-9 expression." (PMID 27028892, 2016). "Given the close association between galectin-9 expression and NK cell numbers, it is reasonable to speculate that a reduced level of galectin-9 in a tumor contributes to the poor infiltration of NK cells into the tumor microenvironment." (PMID 27028892, 2016). "Tumor expression of galectin-9 showed a trend toward improved survival (p = 0.087)." (PMID 26066796, 2015). "To conclude, while tumor cell expression of galectin-9 seemed to represent a beneficial response, galectin-1 expression might be used as a marker for a more aggressive anti-cancer treatment." (PMID 26066796, 2015). "Albeit LGALS9 has not yet been implicated in NSCLC or in a chemotherapy-refractory phenotype of other tumor cells, various galectins such as galectin-1 and -3 were reported to have a role in driving a chemotherapy-refractory phenotype." (PMID 26353782, 2015). "However, apoptosis of TIM-3+ CD8+ T cells through their TIM-3 and tumor-derived galectin-9 reduces effector cell frequency and thereby helps tumors to escape from the immune attack." (PMID 26493689, 2015). "The tumor cells secrete galectin-9, which increases apoptosis of tumor-infiltrating CD8+ T cells." (PMID 26493689, 2015). "Tumor cells secrete galectin-9, which increases apoptosis of tumor-infiltrating CD8+ T cells." (PMID 26493689, 2015). "Tumor expression of galectin-9 showed a trend toward improved survival, which might be related to virus induced expression." (PMID 26066796, 2015). "Tumor cell expression of galectin-9 showed a trend toward improved survival (p = 0.087)." (PMID 26066796, 2015).